BCL2 (BCL2 apoptosis regulator)
Diseases named in the same sentence as BCL2 in open-access papers (continued):
Sharing a sentence is not in itself a finding about the gene and the disease.
pancreatic cancer (continued). "Depletion of RLIP76 by antisense significantly increased the levels of the pro-differentiation marker E-cadherin and pro-apoptotic protein Bim while decreasing the levels of anti-apoptotic protein Bcl2, cyclin B1 and CDK4 in both BxPC3 and Panc-1 pancreatic cancer cells." (PMID 22509328, 2012). "Overexpression of Bax does not influence the apoptosis rate or expression of Bcl-2 and Bcl-xL in human pancreatic cancer cells transduced with a retroviral expression vector." (PMID 24212603, 2010). "We studied the relationship of Shh-Gli1 signaling pathway with proliferation and apoptosis of pancreatic cancer cells and the regulation of transcription factor Gli1 to insulin-like growth factor binding protein 6 (IGFBP6) and Bcl-2 genes at the level of transcription." (PMID 19736394, 2009). "Additionally, KIFC1 depletion led to alterations in the expression of Vimentin, N-cadherin, Bcl-2, E-cadherin, and BAX, suggesting that KIFC1 may contribute to carcinogenesis and progression by influencing apoptosis in pancreatic cancer cells." (PMID 38112634, 2023). "Our study demonstrated that the new compound 2 significantly induced apoptosis in human pancreatic tumor cells (PATU8988T), characterized by the morphologies abnormity, the reduction of cell number, the upregulation of proportion of apoptotic cells, and decrease in the ratio of Bcl-2 to Bax." (PMID 36583050, 2022). "The efficacy of GNE-495 to induce cell death in pancreatic cancer cell lines was also apparent due to its effect on increasing caspase-3 activity, Bax, cleaved -caspase 3 and -PARP expressions, and decreasing Bcl2 expression in a concentration-dependent manners." (PMID 34511598, 2021). "Evidence suggests that CTD exerts cytotoxic effects on pancreatic cancer cells by JNK-dependent pathway, as CTD treatment suppressed pancreatic cancer cell proliferation via stimulating caspase-8 and caspase-9, upregulating expression level of Bad, Bid and Bak, while downregulating Bcl-2." (PMID 32707651, 2020). "Pristimerin-induced inhibition of Bcl-2 (as well as Bcl-2 mRNA) is sufficient to promote mitochondrial permeability transition and release of cytochrome c mediated by Bax and Bak without the inhibition of Bcl-xL in pancreatic cancer cells." (PMID 31354475, 2019). "SCH772984 potentiates the cytotoxic effect of CuB on pancreatic cancer cells through complementary inhibition of EGFR, PI3K/Akt/mTOR, STAT3 and ERK signaling, followed by an increase in the pro-apoptotic protein Bim and a decrease in the anti-apoptotic proteins Mcl-1, Bcl-2, Bcl-xl and survivin." (PMID 29262554, 2017). "Thus, the modulation of these proteins is unlikely to be associated with LBH589-mediated potentiation of TRAIL-induced apoptosis in these cell lines; rather, increase in Bcl-2 and Mcl-1 may counteract LBH589's effect in sensitizing pancreatic cancer cells to TRAIL-induced apoptosis." (PMID 20442774, 2010). "Therefore, enhanced expression of MKP-1, SGK-1, X-IAP and Bcl-2 but not of BAG-1 may be involved in DEX-induced therapy resistance of pancreatic carcinomas." (PMID 16539710, 2006). "Senolysis of GEM‐induced senescent pancreatic cancer cells by ABT‐263 was triggered by a Bcl‐xL inhibitor, but not by a Bcl‐2 inhibitor, suggesting a central role for Bcl‐xL in senolysis." (PMID 38662379, 2024). "Ole (200 μM) raised the ratio of Bax/Bcl2, favoring the apoptotic pathway in MIA PaCa-2 pancreatic cancer cells better than HT (100 μM), although this is not found in healthy cell lines." (PMID 36013319, 2022). "Of note, the combination of Bcl‐2/Bcl‐xL/Bcl‐W antagonists and drugs targeting PDPK1/Akt has thus far not been discussed as a treatment option for pancreatic cancer, further demonstrating the applicability of our model to identify innovative combinatorial approaches." (PMID 32073727, 2020).
follicular lymphoma (263 papers, 1992 to 2026). Follicular lymphoma is a form of non-Hodgkin lymphoma characterized by a proliferation of B cells whose nodular structure of follicular architecture is preserved. "Bcl-2, the founding member of this protein family, is encoded by the BCL2 gene, first described in follicular lymphoma as a result of translocations involving chromosomes 14 and 18, leading to protein overexpression." (PMID 40347842, 2025). "The gene encoding these transcripts (BCL2) seemed to be interrupted in most cases of follicular lymphoma." (PMID 40204952, 2025). "EZH2 mutations and BCL2 translocations are characteristic of both follicular lymphoma (FL) and DLBCL, which has transformed from FL." (PMID 40507898, 2025). "The mutational profile of the current case closely resembles conventional BCL2‐rearranged low‐grade follicular lymphoma, with the notable exception of the IRF4 mutation." (PMID 39415926, 2024). "Overall, the mutation profile of the MYC/BCL2/BCL6-TH group is very similar to that of the MYC/BCL2-DH group, characterised by frequent mutations in follicular lymphoma associated genes (BCL2, CREBBP, KMT2D, EZH2, TNFRSF14)." (PMID 38184753, 2024). "Bcl-2 was initially recognized as an oncogene associated with follicular lymphoma, a type of cancer that originates from B cells." (PMID 39684550, 2024). "Among them, BCL-2 appears to be the most promising candidate due to the extensive literature concerning its role in follicular lymphoma and the significant clustering of synonymous mutations in BCL-2’s BH4 regulatory motif." (PMID 38062391, 2023). "Early studies have found that EZH2 mutations are associated with Bcl-2 rearrangement in follicular lymphoma." (PMID 37988356, 2023). "Follicular lymphoma (FL) is associated with overexpressed BCL-2 and other genetic aberrations, including 6q-." (PMID 37304286, 2023). "Such as overexpression of Bcl-2 caused by chromosomal translocation lead to an increased incidence of follicular lymphoma." (PMID 35236310, 2022). "On the contrary, mutations in KMT2D and BCL2 were more prevalent among follicular lymphoma and DLBCL than in Burkitt Lymphoma." (PMID 33945543, 2021). "Bcl-2 was first discovered via a chromosome translocation that is the hallmark of human follicular lymphoma, and it was subsequently found to promote cell survival as an antiapoptotic protein of the Bcl-2 protein family." (PMID 34348769, 2021). "BCL2 was significantly overexpressed in thyroid, and blocked the apoptotic death of lymphocytes that was thought to be the cause of follicular lymphoma." (PMID 33190424, 2021). "We showed that DLBCL with MYC/BCL2-DH, and those with BCL2 translocation, harbour the characteristic mutation signatures that are associated with follicular lymphoma and its high-grade transformation." (PMID 31844144, 2020). "Bcl-2, the first protein that was associated with translocations identified in follicular lymphoma, contributes to malignancy by inhibiting apoptosis." (PMID 29156646, 2017). "BCL2 translocations are commonly associated with follicular lymphoma and the DLBCL germinal center B-cell-like (GBC) subtype." (PMID 24788952, 2014). "It has been reported that overexpression of Bcl-2, which is caused by chromosomal translocation of the Bcl-2 oncogene into the immunoglobulin heavy chain gene locus, is a characteristic feature of human follicular lymphoma." (PMID 24256941, 2013). "BCL-2 is a proto-oncogene originally associated with the t(12:18) chromosomal translocation, which is the cytogenetic hallmark of follicular lymphoma." (PMID 21689023, 2011). "Whereas increased expression of Bcl-2 promotes malignancies such as human follicular lymphoma, the precise role of the EBV encoded Bcl-2 homolog BHRF1 in EBV-associated malignancies is less well defined." (PMID 21203485, 2010).
follicular lymphoma (continued). "Moreover, beclin-1 physiologically interacts with Bcl-2 (encoded by the BCL2 gene), an important anti-apoptotic protein that is overexpressed and often mutated in follicular lymphoma and DLBCL." (PMID 41415285, 2025). "With the previous data of acquired resistance to VTX due to Phe104 mutations, the Phe104Ile mutation was detected in a patient with relapsed/refractory follicular lymphoma (FL) treated with BCL-2 inhibitor, which lessened the binding of VTX to BCL-2 by approximately 40-fold." (PMID 38069030, 2023). "BCL2 translocation likely represents the first step in follicular lymphomagenesis given its pervasiveness, but these studies demonstrate that it is a weak oncogene requiring further mutations to complete the transformation to follicular lymphoma." (PMID 36599826, 2023). "Notably, the oncogenic role of BCL2 is well-established in follicular lymphomas, where the juxtaposition of IgH-BCL2 is implicated in lymphomagenesis, perturbing normal B lymphocyte apoptosis." (PMID 37849766, 2023). "In addition, overexpression of BCL2 has been reported to cause follicular lymphoma, which can be implicated in MCF7 cells, raising the possibility of increased tumorigenesis and invasiveness in MCF7 cells upon exposure to AB1." (PMID 36233156, 2022). "DLBCL with MYC/BCL2-DH and those with BCL2 translocation alone are most likely derived from follicular lymphoma or its precursor lesion, and acquisition of MYC pathogenic mutations may augment MYC function, resulting in aggressive clinical behaviour." (PMID 31844144, 2020). "BCL2 suppresses apoptosis and constitutive expression is thought to cause follicular lymphoma." (PMID 33037222, 2020). "A chromosomal aberration involving BCL2 may be a cause of follicular lymphoma, also known as type II chronic lymphatic leukemia." (PMID 28368324, 2017). "Overexpression of BCL2 is widely accepted as a hallmark of follicular lymphoma in humans." (PMID 26919255, 2016). "Materials and Methods: Formalin-fixed follicular lymphoma sections were FISH-labeled for BCL2 gene rearrangements and digitally scanned in multilayer Z-stacks." (PMID 41682389, 2026). "Together, these alterations define a molecular profile that is distinct from that of classical BCL2-rearranged follicular lymphoma." (PMID 40861583, 2025). "Aberrant BCL2 expression is frequently seen in follicular lymphoma, whereas its absence in reactive follicles serves as an important discriminating marker." (PMID 40559769, 2025). "Kidney immunohistochemistry was positive for CD19 and CD20 (B-cell markers), as well as CD10 and Bcl2, confirming the follicular lymphoma subtype." (PMID 40342409, 2025). "In NHL, BCL2 over expression is frequently linked to diffuse large B-cell lymphoma (DLBCL) and follicular lymphoma, where it inhibits apoptosis to enhance cell survival." (PMID 40321894, 2025). "Flow cytometry identified a clonal population of CD20+, CD10+, and BCL2+ B cells, consistent with a diagnosis of follicular lymphoma." (PMID 41216114, 2025). "BCL2-R-negative, CD23+ follicle center lymphoma is the only low-grade nodal follicular lymphoma that lacks the IGH::BCL2 gene rearrangement." (PMID 40861583, 2025). "Given fluorescence in situ hybridization (FISH) results showing an IGH/BCL2 fusion, which is commonly seen in follicular lymphoma, the DLBCL was considered to likely be a transformation from the patient’s previous follicular lymphoma." (PMID 39569219, 2024). "Subsequently, BCL-2 was recognized to be overexpressed not only in follicular lymphomas, but in a large number of different types of tumors." (PMID 40150937, 2024). "This nanoprobe enabled the simultaneous and quantitative detection of MPO and BCL2 transcripts in bone marrow FFPE infiltrated by follicular lymphoma cells through spectral imaging analysis." (PMID 39273202, 2024).
follicular lymphoma (continued). "Pathological examination of the core biopsy revealed infiltration of CD10- and BCL2-positive nodular centrocytic infiltration consistent with classical follicular lymphoma." (PMID 38460675, 2024). "In contrast, Bcl-2 was first identified through its translocations in follicular lymphoma, where it inhibits apoptosis, thereby contributing to cancer cell survival." (PMID 39337859, 2024). "In a case with follicular lymphoma, it is illustrated that two clones with an inverse light chain pattern are using the same Bcl2-IgH recombination, indicating a common progenitor cell." (PMID 39214930, 2024). "Low-grade follicular lymphoma samples showed increased BCL2 levels and high-grade lower levels, as would be expected." (PMID 38893249, 2024). "The BCL2-IGH translocation occurs in over 85% of follicular lymphoma and 20% of diffuse large B-cell lymphoma, which are both diseases of mature B cells." (PMID 37790327, 2023). "This family is essentially defined by its founder member, the BCL-2 gene located at chromosome 18, which was first identified by chromosomal analysis of follicular lymphoma." (PMID 37720343, 2023). "B-cell malignancies, such as CLL and follicular lymphomas, are functionally dependent on BCL2 for survival." (PMID 35371054, 2022). "Researchers have found that though follicular lymphoma expresses BCL-2 at high levels, its response to venetoclax is quite low This result contradicts the viewpoint that BCL-2 protein expression and resistance to venetoclax are negatively correlated." (PMID 36313732, 2022). "The relationship between clinical variables as well as BCL2 or CCND3 mutation status and follicular lymphoma survival." (PMID 35795062, 2022). "CLL and follicular lymphoma, which benefit from the use of obinutuzumab, are both characterized by high-level BCL2 expression, whereas DLBCL is a more heterogeneous entity." (PMID 33615197, 2021). "Accordingly, the field is moving away from using these lines, with few exceptions (e.g. the VavP-Bcl2 and Bcl2-Ig mice discussed in the Follicular Lymphoma section)." (PMID 34456919, 2021). "BCL2, a 25 kD protein coded on 18q21.3, was originally discovered as a translocation partner in patients with follicular lymphoma (FL) and other B-cell malignancies." (PMID 34576319, 2021). "Cell fate is determined by the balance of Bcl-2 anti-apoptotic protein expression in relation to pro-apoptotic BH3 proteins levels, highlighted by the discovery of Bcl-2 being the first anti-apoptotic overexpressed oncogene, as seen in follicular lymphoma." (PMID 34753495, 2021). "In R/R follicular lymphoma (FL), despite a high level of BCL2 expression, venetoclax monotherapy has shown limited efficacy, with an ORR of 38% and only 14% CR rate." (PMID 34938664, 2021). "Bcl-2 is an anti-apoptotic gene initially identified in follicular lymphoma, which inhibits apoptosis via a calcium-dependent specific protein phosphorylation mechanism." (PMID 32587801, 2020). "In another study, clonal CD34+CD19+ progenitors were detected in bone marrow of BCL2-IgH-positive follicular lymphoma patients." (PMID 32010428, 2020). "While fluorescence in situ hybridization is frequently used to detect the BCL2 translocation in follicular lymphoma, PCR is generally used to detect this translocation in VRL." (PMID 33505989, 2020). "BCL-XL expression as aprognostic marker in follicular lymphoma should be considered; anexpression of BCL-2 was significantly enhanced in cutaneouslesions of adult and pediatric patients." (PMID 31285648, 2019). "Bcl-2 was first discovered because of its involvement in B-cell malignancies where chromosomal translocations activate the gene in about 80–90% of follicular non-Hodgkin’s lymphomas." (PMID 29944468, 2018). "The abnormal lymphocytes were CD20+, CD10+, BCL-6+ and BCL-2+, consistent with recurrent follicular lymphoma." (PMID 30322385, 2018).
follicular lymphoma (continued). "The deregulation of the “B-cell lymphoma-2” (BCL2) family in mature B cell malignancies has been first highlighted through a translocation between the chromosomes 14 and 18 that led to the overexpression of the Bcl-2 oncogene in follicular lymphoma." (PMID 30666297, 2018). "The founder member, BCL-2, was first identified through chromosomal mapping in follicular lymphoma where constitutive BCL-2 expression is driven from the immunoglobulin locus by the t translocation." (PMID 29769323, 2018). "FISH analysis confirmed the presence of IgH/BCL2 rearrangement in both the low grade follicular lymphoma (FL) and transformed Langerhans cells sarcoma (LCS) samples, demonstrating a clonal relationship." (PMID 30322385, 2018). "Inhibition of BCL-2 using specific BH3-mimetic inhibitor Venetoclax efficiently induces apoptosis in CLL cells in circulation, and is also promising for other BCL-2 dependent malignancies such as follicular lymphoma and a subset of DLBCL." (PMID 30524962, 2018). "Using the Cas9 labels, we mapped a known BCL2–IGH translocation present in the follicular lymphoma cell line DOHH-2, obtained commercially, and detected similar translocations in seven lymph node tissue samples from follicular lymphoma patients." (PMID 29162844, 2017). "As a proof of principle, we used this new “nanomapping” method to detect and map precisely BCL2–IGH translocations present in lymph node biopsies of follicular lymphoma patents." (PMID 29162844, 2017). "Yet only pan-hematopoietic expression of BCL2 via the Vav-BCL2 transgene led to follicular lymphoma development." (PMID 26919255, 2016). "Later, bcl-2 gene amplification was also found in follicular lymphoma and small cell lung cancer, and eventually, about 50% of human cancers have been shown to have an elevated expression of Bcl-2." (PMID 28025559, 2016). "These questions include the following: 1) Is a history of follicular lymphoma predict a worse prognosis in patients with MYC/BCL2 DHL?" (PMID 27203548, 2016). "To distinguish follicular lymphoma (in Vav-Bcl2 mice) from follicular hyperplasia (in Vav-Bcl2/TACI-Ig mice), we used a bioanalytical technique for its investigation, in particular mid-infrared (MIR) imaging." (PMID 26236782, 2015). "To gain a deeper insight into the distinction between follicular hyperplasia and follicular lymphoma, we analyzed tissues from Vav-Bcl2 transgenic mice." (PMID 26236782, 2015). "Overexpression of the anti-apoptotic protein BCL-2 is characteristic of human follicular lymphoma (FL) and some cases of diffuse large B cell lymphoma (DLBCL)." (PMID 25362242, 2014). "Bcl-2, the first apoptotic regulator identified, was originally discovered as the defining oncogene in follicular lymphomas." (PMID 24387269, 2014). "Chromosome 18 gains are very common in follicular lymphomas and are supposed to provide an alternative mechanism for BCL2 activation." (PMID 22937079, 2012). "This pathway is closely regulated by a group of proteins belonging to the Bcl-2 family, named after the BCL2 gene originally observed at the chromosomal breakpoint of the translocation of chromosome 18 to 14 in follicular non-Hodgkin lymphoma." (PMID 21943236, 2011). "The bcl-2 translocation is the most common translocation in cancer, occurring in >90% of follicular lymphomas and a third of diffuse large cell lymphomas." (PMID 20158866, 2010). "Some tumors evade apoptosis and obtain a survival advantage through aberrant Bcl-2 expression and the oncogenic potential of Bcl-2 is well documented in follicular lymphomas." (PMID 20459695, 2010). "The bcl-2/IgH antisense transcript is presumed to be responsible for the overexpressed bcl-2, the root of oncogenicity in follicular lymphomas." (PMID 21311100, 2010).